TIMP1 (TIMP metallopeptidase inhibitor 1)
Diseases named in the same sentence as TIMP1 in open-access papers (continued):
Sharing a sentence is not in itself a finding about the gene and the disease.
myocardial infarction (36 papers, 2011 to 2025). Gross necrosis of the myocardium, as a result of interruption of the blood supply to the area, as in coronary thrombosis. "This is in contrast to a recent study which showed a significant association between plasma TIMP-1-levels and recurrent cardiovascular events in patients suffering from previous myocardial infarction or unstable angina 3–36 months before enrollment." (PMID 28446168, 2017). "In humans, TIMP-1 is mainly expressed in the myocardium by fibroblasts and cardiomyocytes, and its deficiency is associated with cardiac remodeling in the left ventricle following myocardial infarction." (PMID 39682376, 2024). "This study shows cold fibrosis following acute-myocardial infarction and highlights TIMP1 as a therapeutic target to reduce fibrosis." (PMID 39970910, 2025). "Our expression analysis demonstrated that TIMP1 expression was significantly elevated in the acute myocardial infarction group, which is in agreement with the findings from our animal model." (PMID 41393260, 2025). "A biomarker analysis from 389 male patients undergoing coronary angiography identified high plasma TIMP-1 as an independent predictor of myocardial infarction (MI)." (PMID 39195176, 2024). "Singla and McDonald and Glass and Singla showed that TIMP-1 derived from embryonic stem cells improved cardiac remodeling by inhibiting cardiomyocyte apoptosis following myocardial infarction." (PMID 36440183, 2022). "Investigations of TIMP-1 have shown attenuated maladaptive cardiac remodeling at the site of myocardial infarction, inhibition of cardiomyocyte apoptosis, and enhanced pro-vasculogenic factor release from cardiac fibroblasts, including VEGF, FGF, and HGF." (PMID 34639108, 2021). "Importantly, validation in a murine myocardial infarction (MI) model further corroborated these observations, demonstrating significant upregulation of TIMP1 and THBS4 mRNA expression, alongside downregulation of HCLS1." (PMID 41393260, 2025). "Other studies reporting prognostic relevance of MMP-9/TIMP‐1 ratios in a comparable setting of myocardial infarction were conducted in serum, which might explain the disparity our findings." (PMID 31932967, 2021). "In addition, TIMP-1 knockout mice have greater LV dilation and decreased ejection fraction after myocardial infarction, while inhibition of MMPs reverses ECM protein remodeling and compromised cardiac function." (PMID 25823011, 2015). "In this study involving Chinese patients with myocardial infarction and a coronary arteriosclerosis group, elevated levels of both circulating MMP-9 and TIMP-1 were observed." (PMID 39195176, 2024). "In all cases of myocardial infarction, median serum levels of MMP-3 (stromelysin), MMP-9, PAPP-A, TIMP-1 were 14.11 pg/ml, 58.6 pg/ml, 1.3 μg/ml, 93.85 pg/ml respectively whereas the mean serum MCP-1 was 650.57 ± 625.42 pg/ml." (PMID 39351476, 2024). "In a study on myocardial infarctions, matrix metalloproteinases (MMP) 2 and 9 as well as tissue inhibitor of matrix metalloproteinases 1 (TIMP-1) were detected immunohistochemically in mechanically wounded myocardium (ECG electrodes, vessel ligations)." (PMID 34041592, 2021). "Previously, serial samples of ACS patients after myocardial infarction revealed a dynamic quality in the circulating levels of MMP-8, MMP-9, and TIMP-1 in both the acute and the recovery period." (PMID 28278213, 2017). "In addition, in a large prospective cohort study of individuals with and without (presumably type 2) diabetes, increased plasma TIMP-1 levels, measured six months after myocardial infarction, was significantly associated with left ventricular remodeling and adverse outcomes." (PMID 25848912, 2015). "Elevated MMP-1 levels in myocardial infarction patients, without corresponding increases in TIMP-1, correlate with poorer ventricular function." (PMID 39877021, 2024).
Cirrhosis (30 papers, 2011 to 2025). A chronic disorder of the liver in which liver tissue becomes scarred and is partially replaced by regenerative nodules and fibrotic tissue resulting in loss of liver function. "In a retrospective study involving 84 patients with cirrhosis and 14 healthy controls, TIMP-1 levels in arterial and hepatic vein plasma were determined by using ELISA." (PMID 40109726, 2025). "The expression of TIMP-1 is increased in hepatic cirrhosis patients, which is partly caused by matrix stiffness-induced HSC’s elevated exocytosis and secretion of TIMP-1 in a caveolin-1-and dynamin-2-dependent manner." (PMID 36711017, 2023). "The findings demonstrated a substantial positive correlation between TIMP-1 levels and the disease severity in patients with cirrhosis, suggesting that TIMP-1 may be a useful noninvasive marker for anticipating problems associated with cirrhosis." (PMID 40109726, 2025). "In this respect, decreased TIMP-1 suggests an additional increase in extracellular matrix degradation, further ameliorating the existing misbalance between accumulation and degradation of collagens typical of cirrhosis." (PMID 27634375, 2016). "Interestingly, the uppermost values for HA (228.2 ng/mL) and TIMP-1 (845.2 ng/mL) in children correspond to a patient with complete cirrhosis." (PMID 21858035, 2011). "Therefore, we sought to determine expression of the rat genes Mmp2, Mmp9, Timp1 and Timp2 in the liver of CCl4-treated rats with different degrees of cirrhosis." (PMID 21813019, 2011). "Our data showed that the mRNA and protein levels of TIMP-1 were remarkedly increased and the levels of MMP-1 were significantly decreased in the CCl4-induced cirrhosis liver group." (PMID 32928296, 2020). "Although TIMP1, HA and P3NP were better at identifying cirrhosis; OPN and VIM demonstrated superiority at earlier stages of fibrosis." (PMID 30559459, 2018). "In established end-stage injury with cirrhosis there is increased expression of MMP-2, MMP-9, MMP-14 as well as TIMP-1 and TIMP-2." (PMID 25076423, 2014). "TIMP-1 and TIMP-2 expression were significantly increased in a small number of PBC cirrhosis." (PMID 36551935, 2022). "TIMP-1 was reduced in early PBC and viral and alcoholic hepatitis and cirrhosis (p < 0.001)." (PMID 36551935, 2022). "Microscopic examination claimed remarkable downregulation of TIMP-1, Col-I, and α-SMA in the rats’ livers treated with Q-Br in a dose-responsive manner compared to the noticeable downregulation of the same immune-stained proteins from the cirrhosis control." (PMID 36204229, 2022).
osteoarthritis (27 papers, 2005 to 2026). A noninflammatory degenerative joint disease occurring chiefly in older persons, characterized by degeneration of the articular cartilage, hypertrophy of bone at the margins and changes in the synovial membrane. "In summary, this study identifies TIMP1 as a pivotal immunometabolic regulator in osteoarthritis (OA), orchestrating extracellular matrix remodeling, inflammatory signaling, metabolic reprogramming, and gut microbiota dynamics." (PMID 41170378, 2025). "This study highlights TIMP1 as a central immunometabolic regulator in osteoarthritis, integrating extracellular matrix remodeling with inflammatory signaling, metabolic reprogramming, and gut microbiota alterations." (PMID 41170378, 2025). "CD8+ T-cell-induced tissue inhibitor of metalloprotein-1 (TIMP1) expression aggravates osteoarthritis." (PMID 37503333, 2023). "Specifically, key clinical parameter (MMP-3 and TIMP-1) were obtained from blood probes of German shepherd dogs with early osteoarthritis symptoms fed with collagen hydrolysates." (PMID 34677442, 2021). "Effects of SAMC on MMP-9, MMP-13, and TIMP-1 protein expression in osteoarthritis chondrocytes were detected using western blot." (PMID 29333456, 2017). "The study set out to determine the levels of metalloproteinases MMP-1, MMP-3 and MMP-8, as well as tissue inhibitor TIMP-1 in patients with osteoarthritis, following the administration of anti-rheumatic agents." (PMID 32185271, 2017). "In the field of orthopedics, DHEA has been shown to exert beneficial effects on osteoarthritis-damaged cartilage by actively regulating the balance of anabolic and catabolic factors (e.g., MMPs/TIMP-1 and ADAMTS/TIMP-3) and inhibiting catabolic signaling pathways (e.g., Wnt/β-catenin)." (PMID 34090401, 2021). "Furthermore, biochemical parameters are also altered as found in our analysis of the blood-probes with respect to osteoarthritis markers (e.g., TIMP-1, MMP-3)." (PMID 34677442, 2021). "TIMP-2, TIMP-3, and TIMP-4 are elevated in patients with osteoarthritis, while TIMP-1 is decreased." (PMID 32189997, 2020). "Genes procollagen-lysine, 2-oxoglutarate 5-dioxygenase 2 (PLOD2), collagen type I α1 chain (COL1A1), and tissue inhibitor of metalloproteinase 1 (TIMP1) are shown upregulating in osteoarthritis-related fibrosis; they are usually considered to be fibrotic markers." (PMID 31582897, 2019). "The genus Muribaculaceae, enriched following TIMP1 silencing and known for its capacity to produce butyrate and promote immune tolerance, may offer a novel microbial target for modulating the gut–joint axis in osteoarthritis management." (PMID 41170378, 2025). "Metformin also led to an increased expression of TIMP1 and TIMP3 in osteoarthritis chondrocytes co-cultured with metformin-treated adipose tissue-derived human mesenchymal stem cells." (PMID 37313172, 2023). "Additionally, the expression of MMP-3、TIMP-1 in different layers of the articular cartilage was analyzed by immunohistochemistry for 22 KBD patients, 15 osteoarthritis (OA) patients and 21 controls." (PMID 34980041, 2022). "The high expression of TIMP-1, MMP-1 and MMP-13 in the cartilage may be responsible for the degeneration, and PCL rupture may trigger meniscus degradation and ultimately osteoarthritis." (PMID 30626725, 2019). "We determined the interleukin 6 (IL-6), IL-6 receptor α (IL-6Rα), gp130, receptor activator of nuclear factor κB ligand (RANKL), matrix metalloproteinase 3 (MMP3), TIMP metallopeptidase inhibitor 1 (TIMP1), and Bcl-2 levels in RA and osteoarthritis (OA) serum and synovial fluid." (PMID 29755657, 2018).
liver disease (26 papers, 2009 to 2026). "The purpose of this study was to investigate whether several novel markers of liver disease currently utilized in adults and children (HA, TIMP1, PIIINP, ELF) are associated with liver disease in premature baboons receiving PN." (PMID 32150543, 2020). "Key genes such as ALB and TIMP1 emerged as central regulators of HBV-associated metabolic reprogramming and fibrosis, highlighting potential therapeutic targets for HBV-related liver disease." (PMID 40964049, 2025). "The higher expression of TIMP1 in NCC than in NCH or NNCH further confirms the importance of TIMPs/MMPs in the pathogenesis of AATD-related liver disease." (PMID 36768808, 2023). "Both TIMP-1 and TIMP-2 had significant diagnostic ability in detecting advanced liver disease but the status of TIMP-1 and TIMP-2, in the algorithm of NAFLD diagnosis, is yet to be established." (PMID 35743260, 2022). "Further investigations are needed to characterize functional connections between Phb1 and Timp1 in the liver disease model." (PMID 34539442, 2021). "Although there are few data related to TIMP-1 in children as a single marker of liver injury in different hepatic diseases, our results suggested that TIMP-1 would be suitable as a fibrosis marker in HCV children." (PMID 21858035, 2011). "Nevertheless, the expression levels of FoxP3 and TIMP-1 still remained high in the BA liver, suggesting that the expression of these markers may be specifically related to the course of BA over the other inflammatory liver diseases." (PMID 40270513, 2025). "Our findings of greater liver damage, as well as higher HA and TIMP1, in the PRT-IL group of baboons suggest that nutrient deficiency may be an important contributor to neonatal liver disease." (PMID 32150543, 2020). "The findings that hepatic LCN2 expression closely correlated with disease severity (i.e. ABIC and MELD scores), the degree of portal hypertension (i.e. levels of HVPG) and the expression of key fibrogenic genes (i.e. COL1A1, TIMP1) highly suggest a pathogenic role for LCN2 in AH." (PMID 32968110, 2020). "HA and TIMP1 were significantly elevated in preterm baboons with early histological findings of liver disease evidenced by hepatic steatosis, Kupffer cell hypertrophy and a trend towards fibrosis whereas traditional markers of liver disease remained normal." (PMID 32150543, 2020). "Moreover, TIMP-1 has been found to be strongly upregulated in liver tissue and serum during hepatic fibrogenesis in patients with liver disease and in animal models of hepatic fibrogenesis; its expression directly correlates with the stage of hepatic fibrosis." (PMID 28386095, 2017). "Thus, TIMP-1 could represent the missing functional link for the unique association of fibrogenesis and carcinogenesis in chronic liver disease and thereby a promising therapeutic target to prevent not only progression of liver disease but also the development of HCC." (PMID 28386095, 2017). "Most studies of human liver diseases and animal models of progressive fibrosis have demonstrated that TIMP1 mRNA expression was upregulated at early stages of fibrosis and because TIMP1 functions not only reduce MMP activity but also act on the suppression of apoptosis by HSCs." (PMID 23829630, 2013). "Enhanced expression of TIMP-1 and TIMP-2 occurs in rat models of liver injury and in various human liver diseases." (PMID 23516586, 2013). "Although TIMP1 had the greatest ability of the markers examined here to discriminate fibrosis when compared to other novel and traditional markers of liver disease, TIMP1 still did not exhibit as strong a correlation with any of the histopathological findings." (PMID 32150543, 2020). "The Spearman’s correlation coefficients between TIMP1 and markers of liver disease were low and nonsignificant (fibrosis: rs = 0.14, p = 0.40; microvesicular steatosis: rs = 0.14, p = 0.43; and Kupffer cell hypertrophy: rs = 0.18, p = 0.29)." (PMID 32150543, 2020).
liver disease (continued). "TIMP-1 and TIMP-2 are mainly produced by HSCs and are upregulated in various human liver diseases." (PMID 29986685, 2018). "MMP-8, MMP-9, YKL-40, and TIMP-1 serum levels were unaffected by the presence or absence of CF liver disease or pancreatic insufficiency." (PMID 25545245, 2014). "Interestingly, of liver disease-related 5 DE genes between Phb1+/− and WT, the mRNA expressions of forkhead box M1 (Foxm1) and TIMP inhibitor of metalloproteinase (Timp1) were matched with validation for RNA-seq in liver tissues and AML12 cells transfected with Phb1 siRNA." (PMID 34539442, 2021). "Moreover, treatment with MSCs significantly decreased col1 transcripts, with beneficial trends of profibrogenic gene expression of tissue inhibitor of metalloproteinases-1 (TIMP-1) and MMP-2, 8, and 9, confirming that MSC infusions significantly attenuated T2DM-induced liver disease." (PMID 31747961, 2019). "Together, these data indicate that the observed increased expression of MMP-8, MMP-9, YKL-40, and TIMP-1 occur indeed relatively specific for the existence of CF lung disease without being affected by pancreas and liver disease as other major manifestations of CF." (PMID 25545245, 2014).
aneurysm (23 papers, 2012 to 2025). Bulging or ballooning in an area of an artery secondary to arterial wall weakening. "In the mouse genetic model, whereas either MMP-2 or MMP-9 deficiency is resistant to aneurysm formation, disruption of TIMP-1, an MMP-9 inhibitor, leads to exaggerated aneurysm growth." (PMID 22187650, 2012). "Generally, the increase in MMP-9 activity may be a risk of cerebral vascular abnormality and TIMP-1 has a protective role for aneurysm progression." (PMID 25932641, 2015). "In patients with aneurysms of TAA, increased circulating levels of MMP-1, -2 and TIMP-1 were reported and were also associated with the shear stress which, in turn, promotes aortic structure remodeling and consequently favors aneurysm expansion." (PMID 33573220, 2021). "In an elastase-induced murine AAA model, TIMP-1 knockout mice develop bigger aneurysms than corresponding control mice, suggesting TIMP-1 to have a protective effect on AAA formation and growth." (PMID 34572424, 2021). "The co-culture of GFs with AA lesions shows increased expression of TIMP-1, the inhibitor of the aneurysm severity marker MMP-9." (PMID 26110102, 2015). "Within our study, we found significantly higher TIMP-1 values within the control group, which might suggest its protective role against aneurysm formation." (PMID 39408865, 2024). "Between MMPs, MMP-2, -8, -9, and TIMP-1 are overexpressed and hyperactivated in the aneurysm wall." (PMID 33573220, 2021). "For example, the ratio MMP1:TIMP1 mRNAs, which differed between segments (from 0.85 in the proximal part, nearly doubled (1.65) in aneurysm sac and 1.1 in the distal segment) could be a result of dysregulation of their expression in the segments." (PMID 34091862, 2021). "Moreover, only moderate correlation (rS = 0.41) was found between the relative expression of MMP1 and TIMP1 along the aneurysm tissue." (PMID 34091862, 2021). "On the other hand, TIMP-1, the primary endogenous inhibitor of MMP-9, has a protective effect on AAA formation, suggested by the finding that TIMP-1-deficient mice developed larger aneurysms after elastase infusion compared to wild-type mice." (PMID 27455234, 2016). "Conversely, given the relatively straightforward correlation of aneurysm incidence with MMP3 and TIMP1 level, we suppose that these may be the key players in the aortic remodeling upon high-dose AngII." (PMID 33467682, 2021). "TIMP1 expression is reduced in aneurysmal tissues, and the absence of TIMP1 resulted in severe aneurysm in the intraluminal elastase-perfused AAA131 and CaCl2-induced TAA mouse models." (PMID 31857579, 2019). "However, in a modified AAA mouse model induced by CaCl2, a lack of thrombospondin-1 was shown to inhibit aneurysm formation by elevating tissue inhibitor of metalloproteinases-1 (TIMP1) expression but without affecting MMP expression." (PMID 34646388, 2021).